RNU6-817P (RNA, U6 small nuclear 817, pseudogene)
Gene: Small nuclear RNA gene on chromosome 1 (116,413,766 to 116,413,869, reverse strand). Ensembl gene ENSG00000212385.
Homologues: Orthologues: chimpanzee U6 (99% identical), macaque U6 (95% identical), guinea pig U6 (76% identical), dog U6 (71% identical). Paralogues in human: RNU6-1316P (85% identical), RNU6-41P (85% identical), RNU6-1145P (84% identical), RNU6-589P (84% identical), RNU6-1117P (83% identical), RNU6-1181P (83% identical), RNU6-12P (83% identical), RNU6-13P (83% identical), RNU6-146P (83% identical), RNU6-166P (83% identical), RNU6-25P (83% identical), RNU6-26P (83% identical), and 1284 more.